NRIR (negative regulator of interferon response)
Synonyms: lncRNA-CMPK2; lncCMPK2
Gene: Long non-coding RNA gene on chromosome 2 (6,819,463 to 6,840,464, reverse strand). Ensembl gene ENSG00000225964.
Diseases named in the same sentence as NRIR in open-access papers:
NRIR is named in the same sentence as 21 diseases in open-access papers, as found by Europe PMC text mining. Sharing a sentence is not in itself a finding about the gene and the disease. The quoted sentences say what the papers report.
systemic sclerosis (3 papers, 2022). A chronic disorder, possibly autoimmune, marked by excessive production of collagen which results in hardening and thickening of body tissues. "Negative regulator of interferon response (NRIR) is an antisense RNA that was shown to affect the expression of IFN-stimulated genes and its dysregulation contributes to autoimmune diseases such as systemic sclerosis." (PMID 35446871, 2022).
autoimmune disease (2 papers, 2022 to 2025). A disorder resulting from loss of function or tissue destruction of an organ or multiple organs, arising from humoral or cellular immune responses of the individual to their own tissue constituents. "The long non-coding RNA Negative Regulator of Interferon Response (lncRNA NRIR) is widely recognized as a biomarker for certain autoimmune diseases and participates in their pathogenesis." (PMID 41190073, 2025).
diabetes (2 papers, 2020 to 2021). "FFour independent regions in the genome showed evidence of association with progression to diabetes: one region attaining genome-wide significance, 20p12.1 (TASP; P < 5 x 10–8) and three regions with suggestive evidence (P < 8.5 × 10–8), 1q21.3 (MRPS21-PRPF3), 2p25.2 (NRIR), and 3q22.1 (COL6A6)." (PMID 33154504, 2020).
Autoimmunity (1 paper, 2023). The occurrence of an immune reaction against the organism's own cells or tissues. "NRIR has been extensively investigated in previous studies in autoimmunity." (PMID 37475860, 2023).
chronic myelogenous leukemia (1 paper, 2021). "Interestingly, NRIR is located close to the protein-coding gene CMPK2, which is overexpressed in chronic myeloid leukemia K-562 and lymphoblastic leukemia MOLT-4 cell lines, implicating a role in the pathophysiology of these diseases." (PMID 33531590, 2021).
Erythema (1 paper, 2022). Redness of the skin, caused by hyperemia of the capillaries in the lower layers of the skin. "The expression levels of NRIR, USP18, and IFI44 in PBMCs of SLE patients with facial erythema were significantly higher than those in SLE patients without facial erythema." (PMID 35967341, 2022).
HIV-1 infection (1 paper, 2020). The type species of lentivirus and the etiologic agent of acquired immunodeficiency syndrome (AIDS). "Here we show that NRIR transcription is induced in macrophages by all three types of IFNs and also by HIV-1 infection, indicating that NRIR possibly has a negative effect on the IFN response against HIV in macrophages." (PMID 33086748, 2020).
melanoma (1 paper, 2023). A malignant, usually aggressive tumor composed of atypical, neoplastic melanocytes. "NRIR, firstly found to be associated with melanoma by our study, was positively correlated with CYLD, MLKL, STAT1, and TNFSF10." (PMID 37147395, 2023).
Peri-Implantitis (1 paper, 2025). An inflammatory process with loss of supporting bone in the tissues surrounding functioning DENTAL IMPLANTS. "Using loss-of-function approaches, NRIR was determined to be a positive regulator of M1 macrophage activation in peri-implantitis." (PMID 41190073, 2025). "The current study further investigates the role of NRIR in peri-implantitis-associated macrophage polarization." (PMID 41190073, 2025). "Thus, this study investigated the regulatory role and underlying mechanisms of NRIR in macrophage polarization during peri-implantitis." (PMID 41190073, 2025). "Furthermore, supernatants derived from NRIR-knockdown macrophages upregulated osteogenic factor expression in bone marrow mesenchymal stem cells (BMSCs) and alleviated inflammation and bone loss in a rat peri-implantitis model." (PMID 41190073, 2025). "Our previous studies demonstrated significant upregulation of NRIR in peri-implantitis soft tissues." (PMID 41190073, 2025). "NRIR acts as a pro-inflammatory regulator in peri-implantitis." (PMID 41190073, 2025). "Since macrophages are pivotal immune cells in peri-implantitis, we hypothesized that NRIR might regulate macrophage polarization." (PMID 41190073, 2025). "However, our previous studies revealed significant upregulation of NRIR in peri-implantitis, suggesting its potential role in peri-implantitis." (PMID 41190073, 2025). "Next, we explored the role of NRIR in peri-implantitis using a rat model." (PMID 41190073, 2025). "Thus, siRNA targeting NRIR represents a promising treatment strategy for peri-implantitis." (PMID 41190073, 2025). "This study demonstrates that NRIR functions as a pro-inflammatory modulator in peri-implantitis by activating M1 macrophages through the RSAD2/NF-κB axis, providing novel insights into peri-implantitis pathogenesis that may inform future preventive and therapeutic strategies." (PMID 41190073, 2025). "NRIR promotes NF-κB activation through RSAD2, reduces osteogenesis-related factors in BMSCs, and promotes inflammation-induced bone resorption in peri-implantitis." (PMID 41190073, 2025). "In summary, this study elucidates the NRIR/RSAD2/NF-κB pathway regulating M1 macrophage activation, suggesting potential therapeutic targets for peri-implantitis prevention and treatment." (PMID 41190073, 2025).
Sjogren syndrome (1 paper, 2021). An autoimmune disorder in which immune cells attack and destroy the glands that produce tears and saliva. "Moreover, NRIR is abnormally expressed in the peripheral blood mononuclear cells of patients with Sjogren’s syndrome, and it is closely associated with the mRNA functions in immune response and cell metastasis." (PMID 34753383, 2021).
systemic lupus erythematosus (1 paper, 2025). An autoimmune multi-organ disease typically associated with vasculopathy and autoantibody production. "LncRNA Negative Regulator of Interferon Response (NRIR), an interferon-stimulated gene, is widely considered to play an essential role in the pathogenesis of autoimmune skin diseases, such as systemic sclerosis and systemic lupus erythematosus." (PMID 41190073, 2025). "Previous studies have identified NRIR as a potential biomarker for systemic lupus erythematosus (SLE), where it may contribute to disease progression." (PMID 41190073, 2025).
Thrombocytopenia (1 paper, 2022). A reduction in the number of circulating thrombocytes. "We found that SLE patients with thrombocytopenia had considerably lower expression levels of NRIR, RSAD2, and IFI44 than SLE patients with normal platelet counts." (PMID 35967341, 2022).
type 1 diabetes (1 paper, 2020). "We identified one novel region, 20p12.1 (TASP1; genome-wide P < 5 × 10–8) and three regions, 1q21.3 (MRPS21–PRPF3), 2p25.2 (NRIR), 3q22.1 (COL6A6), with suggestive evidence of association (P < 8.5 × 10–8) with progression from islet autoimmunity to type 1 diabetes." (PMID 33154504, 2020).
infection (2 papers, 2016 to 2025). The state of being infected such as from the introduction of a foreign agent such as serum, vaccine, antigenic substance or organism. "In addition, we find that HTNV infection downregulated lncRNA NRIR 48 h post infection, which negatively regulates the transcription of IFITM3." (PMID 28096800, 2016). "CHROMR expression was similarly upregulated by IAV and SARS-CoV-2, infection, while other lncRNAs that were tested were preferably enhanced by either IAV (BISPR, NRIR, CCR5AS) or SARS-CoV-2 (LUCAT1) infection." (PMID 40559622, 2025).
cancer (1 paper, 2021). A tumor composed of atypical neoplastic, often pleomorphic cells that invade other tissues. "Moreover, we also searched and analyzed the expression of lncRNAs FOXD2-AS1 and NRIR in cancer and paracancerous tissues in the TCGA database." (PMID 33777763, 2021).
tumor (1 paper, 2021). "The expression levels of exosomal FOXD2-AS1 and NRIR and XLOC_009459 were significantly decreased after resection of the primary tumor, suggesting that tumor burden may have an impact on the expression level of exosomal FOXD2-AS1 and NRIR and XLOC_009459." (PMID 33777763, 2021). "Finally, this study also confirmed that exosomes could protect lncRNAs from degradation caused by RNase A and make lncRNAs stable in serum, thus suggesting that exosomal lncRNAs FOXD2-AS1, NRIR, and XLOC_009459 could serve as non-invasive tumor markers for CRC diagnosis and early-stage CRC patients." (PMID 33777763, 2021).
NRIR also shares sentences with these, for which no sentence is quoted: B-cell acute lymphoblastic leukemia (1 paper); colorectal cancer (1); hepatitis C virus (1); lymphoblastic leukemia (1); viral infections (1).